HAS2 (hyaluronan synthase 2)
Description:
Catalyzes the addition of GlcNAc or GlcUA monosaccharides to the nascent hyaluronan polymer (Probable). Therefore, it is essential to hyaluronan synthesis a major component of most extracellular matrices that has a structural role in tissues architectures and regulates cell adhesion, migration and differentiation. This is one of three isoenzymes responsible for cellular hyaluronan synthesis and it is particularly responsible for the synthesis of high molecular mass hyaluronan (By similarity).
Tractability: Antibody: UniProt places it where antibodies can reach, with high confidence; its Gene Ontology location is reachable by antibodies, with high confidence; UniProt predicts a signal peptide or a membrane-spanning region. PROTAC: UniProt records ubiquitination sites on it; ubiquitination databases record sites on it.
Gene: Protein-coding gene on chromosome 8 (121,612,116 to 121,641,440, reverse strand). Ensembl gene ENSG00000170961.
Subcellular location: Cell membrane; Endoplasmic reticulum membrane; Vesicle; Golgi apparatus membrane; Lysosome
Pathways (Reactome):
Metabolism: Hyaluronan metabolism
Gene Ontology:
Molecular function: hyaluronan synthase activity; identical protein binding; protein binding
Biological process: cellular response to fluid shear stress; cellular response to interleukin-1; cellular response to platelet-derived growth factor stimulus; cellular response to tumor necrosis factor; hyaluronan biosynthetic process; positive regulation of cell migration; positive regulation of cell population proliferation; positive regulation of monocyte aggregation; atrioventricular canal development; endocardial cushion to mesenchymal transition; extracellular matrix assembly; kidney development; polysaccharide biosynthetic process; positive regulation of urine volume; renal water absorption; vasculogenesis; estrous cycle; positive regulation of hyaluronan biosynthetic process; positive regulation of keratinocyte migration; positive regulation of keratinocyte proliferation; positive regulation of smooth muscle cell migration; positive regulation of substrate adhesion-dependent cell spreading; regulation of extracellular matrix assembly
Cellular component: endoplasmic reticulum membrane; extracellular vesicle; Golgi apparatus; Golgi membrane; lysosome; plasma membrane; UDP-N-acetylglucosamine transferase complex; vesicle; cytoplasm; cytoplasmic vesicle; plasma membrane raft
Genetic constraint (gnomAD): Loss-of-function variants: 13 observed, 48.07 expected, observed/expected ratio (o/e) 0.27, 90% interval 0.17 to 0.43. The upper end of that interval is the gene's LOEUF score, 0.43, which puts it in group 1 of 6, group 1 being the genes least tolerant of losing a copy. Missense variants: 327 observed, 631.35 expected, observed/expected ratio (o/e) 0.52, 90% interval 0.47 to 0.57. Synonymous variants: 211 observed, 226.7 expected, observed/expected ratio (o/e) 0.93, 90% interval 0.83 to 1.04.
Gene-disease validity (ClinGen):
ClinGen rates the evidence that HAS2 causes each of these diseases.
congenital heart disease (autosomal dominant): Limited. A heart disease that is present at birth.
Homologues: Orthologues: chimpanzee HAS2 (100% identical), macaque HAS2 (100% identical), dog HAS2 (99% identical), mouse Has2 (99% identical), rabbit HAS2 (99% identical), rat Has2 (98% identical), guinea pig HAS2 (98% identical), tropical clawed frog has2 (90% identical), pig HAS2 (84% identical), zebrafish has2 (81% identical). Paralogues in human: HAS3 (70% identical), HAS1 (54% identical).
Diseases named in the same sentence as HAS2 in open-access papers:
HAS2 is named in the same sentence as 157 diseases in open-access papers, as found by Europe PMC text mining. Sharing a sentence is not in itself a finding about the gene and the disease. The quoted sentences say what the papers report.
breast cancer (73 papers, 2011 to 2025). A primary or metastatic malignant neoplasm involving the breast. "In breast cancer stem cells (BCSCs) the overexpression of the HAS2 is implicated in the new synthesis of hyaluronic acid, a major polysaccharide component of the ECM which drives the physical interaction to TAMs, via CD44 receptor expressed on their surface." (PMID 39981232, 2025). "Gene expression analysis also demonstrates an association between increased levels of HAS2 expression and a tumor promoting inflammatory gene signature in human breast cancer tissues." (PMID 32455980, 2020). "Remarkably, all but two of the 523 tumor-associated changes in HAS2 were amplifications or up-regulations suggesting that enhanced HA synthesis is frequent in breast cancer." (PMID 32774770, 2020). "We next addressed the association between HAS2 amplification and overall survival in breast cancer patients." (PMID 31645543, 2019). "In breast cancer cell lines HA is synthesized mainly by HAS2, which was already shown to be implicated in cancer progression." (PMID 28086235, 2017). "Our in vivo study with a conditional transgenic mouse model allowing Has2 overexpression in breast cancer demonstrated that HA overproduction caused rapid development of aggressive breast carcinoma at a high incidence." (PMID 26322272, 2015). "HAS2 is expressed in most tissues including skin and mammary gland ductal epithelial and stromal cells, and elevated HAS2 expression has been linked to promoting breast cancer progression." (PMID 34827550, 2021). "Importantly, our laboratory results were supported by human breast cancer patient data, where increased HAS2 expression was significantly associated with a tumor promoting inflammatory gene signature." (PMID 32455980, 2020). "However, HAS2 expression is particularly linked to triple negative and basal-like breast cancer subtypes and its elevated expression is associated with reduced overall survival of these cancer patients." (PMID 26106384, 2015). "Depletion of macrophages reduced both tumor angiogenesis and lymphangiogenesis in HA-producing tumors, and disruption of the Has2 gene in tumor-associated fibroblasts (TAFs) led to impairment of macrophage infiltration following inoculation of mammary carcinoma cells into nude mice." (PMID 26322272, 2015). "It has been demonstrated that HAS2 is required for the induction of the EMT program mediated by TGF‐β specifically in breast cancer cells coupled with the participation of hyaluronan receptor CD44." (PMID 40542654, 2025). "In highly metastatic breast cancer, CSCs express hyaluronan synthase 2 (HAS2), which is crucial for creating a pro-metastatic microenvironment." (PMID 39981232, 2025). "Research findings from breast cancer cells indicate that endorepellin is also involved in autophagosomal degradation of HAS2, reducing extracellular hyaluronan in TME, which limits cell proliferation and angiogenesis." (PMID 40542654, 2025). "On the contrary, the transfection of HAS2 siRNA can inhibit the development of breast cancer and the occurrence of metastatic colonization through the EGF-mediated kinase/PI3K/Akt signalling pathway." (PMID 36698043, 2023). "HAS2 promotes the invasion of breast cancer cells by decreasing tissue metalloproteinase inhibitor 1 (TIMP-1)." (PMID 36613567, 2022). "Conversely, inhibition of HAS2 leads to reduced tumor cell migration, diminished tumor cell proliferation, and improved chemotherapy sensitivity in breast cancer and cells." (PMID 36613567, 2022). "In agreement with our previous studies, the breast cancer cells that metastasize to bone marrow expressed higher level of HAS2 than the parental cells." (PMID 36497283, 2022). "In contrast to our qPCR results, it was reported for breast cancer that HAS2 knockdown in Hs578T cancer cells leads to an upregulation of HAS1, HAS3 and HYAL1." (PMID 35767191, 2022).
breast cancer (continued). "This also fits with the statements of Okuda and colleagues that high HAS2 expression in breast cancer cells correlates with increased growth and metastasis than control cells." (PMID 35767191, 2022). "In this work, we presented a new finding on hyaluronan synthase 2 (HAS2) and the related membrane cytoskeletal cross linker protein, Ezrin, on antiestrogen resistance of receptor-positive (ER+) breast cancer cells." (PMID 36386154, 2022). "HA generation was enhanced in doxorubicin-resistant breast cancer MCF7 cells via the upregulation of HA synthase-2 (HAS2)." (PMID 36289931, 2022). "The PI3K pathway was activated by HAS2 overexpression in breast cancer, enhancing the expression of ABCB1/MDR1 and thus contributing to treatment resistance." (PMID 36613567, 2022). "With the present study we demonstrate that in vitro c10orf118 induced HA secretion by acting on the up-regulation of the HAS2 gene in fibroblasts and was also identified in tissue specimen of patients diagnosed with breast cancer." (PMID 33807583, 2021). "HAS2 increases breast cancer cell invasion through inhibiting tissue metalloproteinase inhibitor 1 (TIMP-1)." (PMID 33892667, 2021). "Considering the effects sHA of on the breast cancer cells’ functional properties, the correlation between these changes and modulations to the expression of HA partners, such as HA synthases (HAS2 and -3) and CD44, was investigated." (PMID 34944559, 2021). "Taken together, these analyses uncover HAS2 as a stromal gene highly correlated with NRG1 in luminal breast cancer patients." (PMID 33692466, 2021). "Real-time PCR results showed that neutralization of c10orf118 protein in MCF-7 CM diminished the induction of HAS2, confirming that this protein secreted by breast cancer cells plays a key role in the stimulation of HA synthesis in stromal cells." (PMID 33807583, 2021). "Recently, a new secreted protein produced in high amounts by breast cancer cells was found to be an important regulator of HAS2 in stromal cells." (PMID 34360868, 2021). "More specifically, in an in vitro model of co-culture of fibroblasts with breast cancer cells, the protein c10orf118 was shown to induce a significantly increased amount of secreted HA due to the increased levels of stromal HAS2." (PMID 34360868, 2021). "All three HA synthases are upregulated during cutaneous wound repair and in some cancers but, primarily, HAS2 is upregulated in breast cancer." (PMID 34827550, 2021). "We have previously reported OPN-induced up-regulation of HAS2 in 21NT breast cancer cell lines is necessary for both anchorage-independent growth and adhesion of tumor cells to bone marrow endothelial cells." (PMID 31570773, 2020). "Because HAS2 can be expressed by both tumor and stromal cells, tumor cell-specific gene expression levels of HAS2 were evaluated within an expanded panel of breast cancer cell lines that included ER+, HER2+ and triple negative subtypes." (PMID 32455980, 2020). "Ultimately, our findings suggest that HAS2 expression supports a chronic inflammatory state within human breast cancer, which has been shown to foster tumor progression." (PMID 32455980, 2020). "Here we confirmed that 1,25D3 reduces both HAS2 gene expression and hyaluronic acid (HA) synthesis in multiple models of breast cancer." (PMID 32774770, 2020). "In breast cancer, overexpression of hyaluronan synthase 2 increases ErbB2-dependent signaling leading to disease progression, while its suppression leads to an inhibition of tumorigenesis and progression in breast cancer." (PMID 32961706, 2020). "Collectively, these data suggest that, like murine mammary tumor cells and HMLE model systems, 1,25D3 suppresses HAS2 and HA synthesis in association with growth inhibition of human TNBC cells." (PMID 32774770, 2020). "On the other hand, the knockdown of HAS2 in breast cancer cells suppressed their invasive capacity, which was rescued by HAS2 overexpression." (PMID 33171800, 2020).
breast cancer (continued). "The clinical relevance of HAS2 in human breast cancer was assessed in the METABRIC dataset accessed via cBIO Portal." (PMID 32774770, 2020). "This was supported by our recent finding that GFAT and HAS2 were co-expressed in malignant breast cancer cells." (PMID 33171800, 2020). "In accordance with the gene amplification results, HAS2 was transcriptionally active in aggressive metaplastic breast cancer." (PMID 31645543, 2019). "As examples, MMTV-Neu mice over-expressing a HAS2 transgene exhibit increased mammary tumor incidence and growth compared to wildtype animals." (PMID 31134064, 2019). "Conversely, HAS2 knockdown in metastatic breast cancer cell lines arrests tumor cells in G0/G1 as a result of reduced cyclin A, B, and cdc2 expression." (PMID 31134064, 2019). "HAS2 was amplified in 13% of all breast cancers and 25% of metaplastic breast cancers, the latter being rare and aggressive variants." (PMID 31645543, 2019). "Kaplan–Meier survival analysis of breast cancer patients (n = 148) demonstrated co-expression of GFAT and HAS2 to be more significantly associated with worse overall patient survival than the respective expression of GFAT or HAS2 alone." (PMID 31645543, 2019). "Stable knockdown of this HAS in MDA-MB-231 breast cancer cells decreases their invasion, which is rescued by HAS2 re-expression." (PMID 31134064, 2019). "In breast cancer, overexpression of HAS2 was reported to stimulate ABCB1 expression through the PI3K pathway, increasing resistance to doxorubicin." (PMID 31443261, 2019). "The coordinated regulation of GFAT and Has2 gene expression was further supported by the result that GFAT1 knockdown in MMTV-PyVT mammary carcinoma cells significantly reduced Has2 gene expression." (PMID 31645543, 2019). "Overexpression of HAS2 promoted EMT in breast cancer cells (MCF-10) and Madin-Darby canine kidney epithelial cells." (PMID 30513961, 2018). "Overexpression of HAS2 in breast cancer stimulated ABCB1/MDR1 expression through the PI3K pathway increasing resistance to doxorubicin." (PMID 30513961, 2018). "Silencing of HAS2 correlates with increased expression of tissue metalloproteinase inhibitor 1 (TIMP-1) leading into decreased invasive capability in breast cancer cells." (PMID 29914429, 2018). "Previously it has been shown that osteopontin-induced HAS2 expression leads to increased hyaluronan synthesis, elevated proliferation and anchorage-independent growth of breast cancer cells." (PMID 29914429, 2018). "Higher levels of ESRP1, as well as higher ratios of ESRP1/ZEB1 and/or ESRP1/HAS2, canpredict poor survival in multiple breast cancer datasets." (PMID 31069317, 2018). "In breast cancer cells knockdown of HAS2 inhibits cell proliferation, migration and invasion, increases apoptosis and number of the cells in G0/G1 cell cycle arrest, while high HAS2 expression in stromal cells associates with decreased survival." (PMID 29914429, 2018). "In line with our findings, HAS2 was shown to promote tumor growth and metastases in bones by stimulating the interaction of breast cancer stem-like cells with macrophages and stromal cells." (PMID 28086235, 2017). "Recently, it was shown that excess of HA generated by a HAS2 transgene in a mouse model for breast cancer, accelerated the development of carcinoma." (PMID 28086235, 2017). "In breast cancer, overexpression of hyaluronan synthase 2 increases ErbB2-dependent signalling leading to disease progression, while suppression of hyaluronan synthase 2 leads to inhibition of tumorigenesis and progression of breast cancer." (PMID 27928742, 2017). "Hyaluronan accumulates in rapidly remodeling tissues, such as breast cancer, due to deregulated expression of the HAS2 gene and/or alterations of HAS2 activity." (PMID 28604766, 2017). "Vice versa, overexpression of ZEB1 in the epithelial MCF7 breast cancer cell line resulted in downregulation of E-cad and a slight activation of HAS2." (PMID 28086235, 2017).
breast cancer (continued). "Expression of ZEB1 and HAS2, the main synthase of HA in tumor cells, was strongly correlated in breast cancer cell lines and tumor patient samples and high expression levels of HAS2 were associated with poor survival." (PMID 28086235, 2017). "Elevated HAS2 expression was correlated with an EMT phenotype in over 70% of metaplastic breast carcinoma." (PMID 28086235, 2017). "In particular, HAS2 has been shown to suppress tissue metalloproteinase inhibitor 1 which increases the invasiveness of breast cancer cells." (PMID 27184066, 2016). "The functional importance of HA in tumor progression was also demonstrated in our recent study using an HA-overproducing breast cancer model in Has2 transgenic mice." (PMID 26322272, 2015). "Cell culture studies show that invasive breast cancer cells synthesize and accumulate larger amounts of HA than normal tissue and preferentially express more HAS2 mRNA than less aggressive tumor cells." (PMID 26106384, 2015). "Aggressive ovarian and breast cancer cells express high levels of HA synthase 2 (HAS2) and lower levels of HA synthase 3 (HAS3) compared to non-aggressive cancer cells." (PMID 25852691, 2015). "Specifically, HAS1 expression in breast carcinoma cells associated with a high relapse rate and short overall survival, while expression levels of stromal HAS1 and HAS2 were positively related to tumor size and lymph node metastasis." (PMID 26322272, 2015). "In breast cancer, expression of HAS2 is mainly in metaplastic carcinomas of breast, which is a subtype related to the EMT, and less expressed in invasive ductal carcinomas." (PMID 25126569, 2014). "A previous study described siRNA-mediated knockdown of HAS2 and the resulting reduction of cell growth and cellular migratory and invasive potentials in human breast cancer cells." (PMID 23426189, 2013). "In human breast cancer cells, the rate of cell proliferation often correlates with HA synthesis and HAS2 expression." (PMID 23426189, 2013). "In accord with our results, increased chemotherapy resistance was observed in MCF7 breast cancer cells overexpressing Has2." (PMID 24124770, 2013). "Furthermore, the mRNA levels of HAS2 are significantly higher in TNBC cell lines than in cell lines from less aggressive ER+ breast cancer." (PMID 41227309, 2025). "However, studies in breast cancer (BC) demonstrate predominant cytoplasmic localization, where it regulates the stability of downstream target HAS2." (PMID 40723784, 2025). "It is well known that HAS2 promotes breast cancer cell invasion through the CD44 pathway." (PMID 37064130, 2023). "This may point to a different regulation of HAS2 expression in the hormone-positive breast cancer cell lines." (PMID 36386154, 2022). "The highly invasive breast cancer cell line Hs578T expresses predominantly HAS2 mRNA." (PMID 36497283, 2022). "Taken together, these data suggested that there might be a HAS2-Ezrin-ER axis in regulating the acquired antiestrogen resistance of ER+ breast cancer." (PMID 36386154, 2022). "Besides this, it has been reported that HAS2 knockdown in breast cancer cells leads to a downregulation of HYAL2 and CD44." (PMID 35767191, 2022). "Moreover, it must be noted that in a previous study from our group, knock-down of HAS2 in the same breast cancer cell line (Hs578T) reduced cyclin B levels while incubation of the cells with fragmented hyaluronan induced its expression (Yuejuan Li, et." (PMID 36497283, 2022). "In contrast to HAS2 or hyaluronan up-regulation in BrCa we found a significant decrease of HAS2 expression after endocrine resistance is acquired in estrogen receptor-positive (ER+) breast cancer cells, with a predictable down expression of ER." (PMID 36386154, 2022). "In breast cancer patients, higher HAS2 expression is a poor prognostic factor." (PMID 35264144, 2022).